RNU6-956P (RNA, U6 small nuclear 956, pseudogene)
Gene: Small nuclear RNA gene on chromosome 7 (94,712,409 to 94,712,511, forward strand). Ensembl gene ENSG00000239030.
Homologues: Orthologues: chimpanzee U6 (99% identical). Paralogues in human: RNU6-10P (83% identical), RNU6-1251P (83% identical), RNU6-480P (83% identical), RNU6-1078P (83% identical), RNU6-838P (83% identical), RNU6-16P (82% identical), RNU6-33P (82% identical), RNU6-38P (82% identical), RNU6-468P (82% identical), RNU6-46P (82% identical), RNU6-476P (82% identical), RNU6-836P (82% identical), and 1285 more.